SLC25A5 (solute carrier family 25 member 5)
Diseases named in the same sentence as SLC25A5 in open-access papers (continued):
Sharing a sentence is not in itself a finding about the gene and the disease.
ovarian carcinoma (1 paper, 2022). A malignant neoplasm originating from the surface ovarian epithelium. "The analysis based on CCLE data suggested that some members of SLC25 family were highly expressed in breast, colorectal, stomach, liver, lung, and ovarian cancer cells, including SLC25A5, SLC25A6, and SLC25A8." (PMID 36254139, 2022).
prion disease (1 paper, 2025). A transmissible disease that is caused by a protein that is able to induce abnormal folding of normal cellular proteins, leading to characteristic spongiform brain changes, which are associated with neuronal loss without an inflammatory response. "We compare down/up-regulated proteins from C− versus 5RINM with altered proteins related to chemical carcinogenesis, reactive oxygen species (e.g., down-regulated P48962/Slc25a4, P51881/Slc25a5, Q9CQQ7/Atp5f1, or P12787/Cox5a), and prion disease (e.g., down-regulated Q05144/Rac2)." (PMID 40006055, 2025).
prostate carcinoma (1 paper, 2022). A carcinoma that arises from epithelial cells of the prostate gland. "SLC25A5 promotes apoptosis through the regulation of bcl-2, caspase-3, and bax in prostate cancer." (PMID 35840882, 2022).
renal carcinoma (1 paper, 2025). A carcinoma arising from the epithelium of the renal parenchyma or the renal pelvis. "Given the strong link between renal cancer and metabolism, we prioritized SLC25A5, HEL-S-87p and ACAT1 as our metabolic targets." (PMID 40790033, 2025).
schizophrenia (1 paper, 2018). A major psychotic disorder characterized by abnormalities in the perception or expression of reality. "The SLC25A5, NONO, LMNA and RPS3A proteins were not chosen for validation because little information about the relation between schizophrenia and these proteins is available." (PMID 29514709, 2018).
viral infection (1 paper, 2022). "SLC25A5 was the most succinylated protein during viral infection, whose specific inhibitors clodronate disodium salt and Empirical Formula (Hill Notation) could significantly repress SARS-CoV-2 replication in both two cell lines." (PMID 35858407, 2022).
tumor (21 papers, 2007 to 2026). "Rescue experiments showed that EIF3A overexpression partially reversed the tumor-suppressive effects of SLC25A5." (PMID 42196314, 2026). "Using value of IOD, quantification of immunohistochemical analysis showed that protein expressions of CYBB, IL1A, IL1B, and SLC25A5 were significantly higher in CESC tissues than in adjacent non-tumor tissues (P < 0.001)." (PMID 36253777, 2022). "We found that DYNLT1, IMMT, RAB2A, and SLC25A5 were tumor biomarkers to assess the prognosis of BRCA patients, and all of them were high-risk genes, and the parameters indicated that 4 genes would make the prognosis of BRCA poorer." (PMID 35919504, 2022). "SLC25A5 results significantly upregulated in 9 cancer tissues and significantly downregulated in 3 cancer tissues, out of the 21 “tumor vs. normal” tissue pairs." (PMID 33396658, 2020). "Various forms of cellular senescence are accompanied by repression of solute carrier family 25 member 5 (SCL25A5) coding for ADP/ATP translocase 2 (ANT2;), which has been implicated in glycolytic metabolism of tumor cells." (PMID 29615539, 2018). "This study investigated whether SLC25A5 exerts tumor-suppressive functions in CRC." (PMID 42196314, 2026). "Among them, TAZ was up-regulated in tumor tissue compared with para-cancerous tissue, and the expression of the remaining eight genes (including SLC25A4, SLC25A5, PARK, PINK1, MFN2, HUWE1, VPS13D, and LRBA) was down-regulated in tumor tissue." (PMID 38373978, 2024). "SLC25A5 and CDKN2A were found to be significantly up-regulated in tumor samples after we conducted differential analysis on these 14 CRCGs." (PMID 36980514, 2023). "We first analyzed the differential expression of 14 CRCGs in five GEO datasets, and the results displayed that SLC25A5 and CDKN2A were significantly up-regulated in tumor samples." (PMID 36980514, 2023). "Genes such as ARF1, SLC25A5, and CDKN2A were significantly up-regulated in tumor samples, while genes such as SNCA, PRNP, and GLS were significantly down-regulated in tumor samples." (PMID 36980514, 2023). "Representative pictures showed that SLC25A5 and SLC25A24 were differentially expressed in tumor and adjacent normal tissues." (PMID 35288533, 2022). "Timer2 analysis shows that SLC25A4, SLC25A5, and SLC25A6 genes are differentially expressed in 16, 12, and 9 tissues out of the available 21 “tumor vs. normal” tissue pairs, respectively." (PMID 33396658, 2020). "Although SLC25A5, ACSF2, MFF, and PMAIP1 have not been previously linked to PE, they are known to significantly influence mitochondrial function and tumor cell death." (PMID 39916955, 2024). "SLC25A5 is strongly over-expressed in various types of human cancer cells, while the role of CD99 in cancer is more controversial, since it behaves as an oncogene in most cancers, whereas in some types of neoplasia it behaves as a tumor suppressor gene." (PMID 34360846, 2021). "Furthermore, in this study, we demonstrated that SLC25A5, PPIA, and TNFRSF10B were correlated with tumor immune microenvironment infiltration and may be potential prognostic biomarkers for ESCA." (PMID 35840882, 2022).
cancer (19 papers, 2007 to 2026). A tumor composed of atypical neoplastic, often pleomorphic cells that invade other tissues. "However, several genes such as SLC25A4 and SLC25A5 showed low mutation frequency in most cancer with an overall average mutation rate of 0.100189." (PMID 36254139, 2022). "SLC25A5 was downregulated in cancer, and its upregulation was related to better overall survival in patients from public datasets and in clinical cases." (PMID 35288533, 2022). "The study indicated that phase I transcripts, ADH1C and GGT5, phase II NQO2, and phase III SLC25A5 may have diagnostic and therapeutic potential in CRC due to their differential expression in the early phase of this cancer." (PMID 41465541, 2025). "As revealed by IHC staining analysis, the proteins of CYBB, IL1A, IL1B, and SLC25A5 were mainly found in cancer cells’ nucleus, cytoplasm, and membranes; brown staining indicated positive staining; and these NRG proteins were either weakly expressed or not expressed in normal tissues." (PMID 36253777, 2022). "In addition, gene sets enriched in cancer-related phenotypes and signaling pathways for SLC25A5 and SLC25A24 were also investigated." (PMID 35288533, 2022). "SLC25A4 and SLC25A5 might be involved in some carcinogenic pathways and metabolic pathways regulated by genetic variation, participating in cancer initiation and development." (PMID 36254139, 2022). "For instance, based on its high expression in cancer cells, SLC25A5 (ANT2) was postulated to preferentially import ATP made by glycolysis, an activity that maintains the mitochondrial membrane potential and by extension, other essential mitochondrial functions." (PMID 30766870, 2019). "SLC25A5 (solute carrier family 25, member 5) is highly expressed in cancer cells, and SLC25A6 (solute carrier family 25, member 6) is an enzyme involved in exchanging ADP/ATP through mitochondrial membranes and its expression has been shown to induce apoptosis in cellular culture." (PMID 29509794, 2018). "The protein expression of SLC25A4, SLC25A5, and SLC25A6 was consistent in top 10 common cancer types." (PMID 36254139, 2022). "Among these, the ADP/ATP translocase 2 (SLC25A5, also known as Adenine nucleotide translocase-2, ANT2) has been previously reported to be overexpressed in CRC and other cancer models." (PMID 31557914, 2019). "Differential expressions in the initial stage of cancer (CSI or CSI and CSII), such as for ADH1C, GGT5, NQO2, and SLC25A5 (bolded), may indicate them as candidates for diagnostic biomarkers." (PMID 41465541, 2025). "SLC25A5 is named adenine nucleotide translocator 2 and presents as a gated pore exchanging ATP for ADP and is considered to have a correlation with glucose accumulation in various types of cancer." (PMID 35288533, 2022). "Combining previous researches and our results, we speculated SLC25A4, SLC25A5, SLC25A9, and SLC2512 might participate in metabolic reprogramming and cancer initiation and development via these oncogenic and metabolic pathways." (PMID 36254139, 2022). "Additionally, they compared the mitochondria of cancer to that of normal cells, showing a significant increase in IMM potentials and the number of transporters, including SLC25A5, which shares many features with SLC25A6, to be strongly overexpressed in different types of cancers." (PMID 37762371, 2023). "Furthermore, ATP2A2 and SLC25A5 demonstrated a stronger positive correlation with NAAD+ in S-231 than in P-231 and confirmed the positive correlation between NAAD+ and the Ca2+ signaling pathway in stem-like cancer cells." (PMID 27391070, 2016). "Among the set of genes that we identify as being related to RCC, some were known from previous studies (e.g. ATP6V1B1, EGLN3, SLC25A5, TUBB, ALDOA); others had never before been associated with RCC, but have been identified with other cancers (e.g. ABL2, JAZF1, TFAP2A)." (PMID 19455236, 2007).
cancer (continued). "While SLC25A5 is a well-characterized mitochondrial ADP/ATP transporter, its potential non-canonical roles in cancer remain unclear." (PMID 42196314, 2026).
neurodegenerative disease (2 papers, 2022). A disorder of the central nervous system characterized by gradual and progressive loss of neural tissue and neurologic function. "The DEG SLC25A5 was involved in the “mitochondrial dysfunction in neurodegenerative diseases” enriched pathway, as the adenine nucleotide translocases protein group (ANT)." (PMID 35804531, 2022).
neurological disease (2 papers, 2018 to 2022). "There were three proteins associated with neurological disease as well as tissue development, including ADP/ATP translocase 2 (Slc25a5), 2′,3′-cyclic-nucleotide 3′-phosphodiesterase (Cnp), and sodium/potassium-transporting ATPase subunit beta-1 (Atp1b1)." (PMID 30127667, 2018).
SLC25A5 also shares sentences with these, for which no sentence is quoted: thyroid (5 papers); infection (4); thyroid cancer (4); hypothyroidism (2); lung carcinoma (2); lymph node metastasis (2); myocardial ischemia (2); papillary thyroid cancer (2); Acute hepatic failure (1); Allergy (1); anaplastic thyroid carcinoma (1); asthma (1); autism (1); autoimmune thyroid disease (1); cervical adenosquamous carcinoma (1); cyst (1); diabetes (1); endocervical adenocarcinoma (1); endothelial dysfunction (1); fibrosis (1); gastrointestinal disorders (1); glioblastoma (1); heart failure (1); hematological malignancy (1); Hydrocephalus (1); hyperthyroxinemia (1); kidney cancer (1); multinodular goiter (1); multiple myeloma (1); non-small cell lung carcinoma (1).
A further 7 diseases each share a sentence with SLC25A5 in 1 paper.